TWIST1 (twist family bHLH transcription factor 1)
Diseases named in the same sentence as TWIST1 in open-access papers (continued):
Sharing a sentence is not in itself a finding about the gene and the disease.
tumor (continued). "Cancer-related genes such as FAS, P16, P21, Twist1, which mainly function as tumor suppressor genes, are inhibited by the overexpression of SUV39H2, while oncogenes such as PSA and C-myc are enhanced by the overexpression of SUV39H2." (PMID 39981438, 2025). "SDEVs from 4T1 cells expressing control shRNA or Twist1 shRNA cell tumor-bearing mice were intravenously injected into recipient mice, followed by microinjection with lucifer yellow into pyramidal neurons from layer II/III of the mPFC." (PMID 40963917, 2025). "In particular, CCL2 binds to its receptor CCR2 and induces the expression of EMT-TFs Snail1 and Twist1 in cancer cells, producing morphological changes to support tumour cell migration toward SCs." (PMID 40037534, 2025). "Specifically, as a key EMT regulator, TWIST1 plays a crucial role in the detachment of tumor cells from the primary site and their migration to other tissues." (PMID 40066442, 2025). "In this study, we established a stable 4T1 cell line expressing Twist1 shRNA and confirmed a significant reduction in tumor cell-derived EVs-packaged Twist1." (PMID 40963917, 2025). "TWIST1 and CREB3L1 are associated with tumor progression mediated by CAF-induced ECM remodeling and fibrosis." (PMID 40755770, 2025). "Tumor cell-derived Twist1 is transported via EVs in the bloodstream to the mPFC, where it subsequently induces dendritic atrophy and depressive-like behaviors in mice." (PMID 40963917, 2025). "Throughout this study, the increased Twist1 expression in the mPFC of tumor-bearing mice was primarily attributed to tumor-derived EVs." (PMID 40963917, 2025). "Consistent with our prior findings, knockdown of tumor cell-derived Twist1 prevented the pro-depressant effects of intravenous administration of SDEVs from 4T1 cell tumor-bearing mice at both behavioral and biochemical levels." (PMID 40963917, 2025). "We show that genetic ablation of endothelial Twist1, as well as pharmacological inhibition of Twist1, reduces Mφ-mediated tumor immunosuppression and circumvents tumor resistance to CAR T cell immunotherapy." (PMID 38416830, 2024). "TWIST1 (Twist related protein 1) is a tumor protein that plays an important role in tumor metastasis and drug resistance." (PMID 39100077, 2024). "As a transcription factor, SOX5 regulates the expression of Twist1 by binding to conserved Sox5 binding sites in the Twist1 promoter, and Twist1 promotes tumor metastasis by inducing EMT." (PMID 38835366, 2024). "EMT is a critical process that contributes to tumor progression and metastasis, and Twist1 has been identified as a key player in EMT in PTC via the NF-κB pathway." (PMID 38779358, 2024). "TWIST1 is highly expressed in MPNSTs, and the TWIST1-miR-214 axis promotes tumor progression by targeting the tumor suppressor gene PTEN, which negatively regulates the PI3K/AKT signaling pathway." (PMID 39594601, 2024). "In a parallel study, similar therapeutic results were observed in a GL261 syngeneic mouse GBM model, collectively suggesting that pharmacological inhibition of Twist1 by harmine overcomes tumor resistance to CAR T cell therapy in GBM." (PMID 38416830, 2024). "For in vivo analysis, we crossed Twist1fl/fl mice with Cdh5-Cre mice to generate an EC-specific Twist1 knockout mouse line, Cdh5-CreERT2;Twist1fl/fl, and used this line to investigate the role of endothelial Twist1 for tumor immunity regulation." (PMID 38416830, 2024). "Our present work reveals an additional role for EC plasticity in tumor immunity regulation, acting via a Twist1-mediated paracrine effect on tumor Mφs." (PMID 38416830, 2024). "Tumor cell-specific knockout of Twist1 in the mammary gland tumors of a genetically engineered mouse model largely prevented these tumor cells from undergoing EMT, intravasation, and distant metastasis." (PMID 38893094, 2024).
tumor (continued). "TRIM28 promotes epithelial-to-mesenchymal transition (EMT) and metastasis of tumor cells through stabilization of Twist-related protein 1 (TWIST1) and activation of Wnt/β-catenin signaling." (PMID 39532800, 2024). "In vitro, experiments demonstrated that Snai1 (similarly Slug and Twist1) regulates endothelial permeability, permissiveness for tumor cell transmigration, and tip/stalk cell formation." (PMID 39095583, 2024). "According to their expression in TCGA patients, both unpaired and paired analyses indicated that BMP2 and TWIST1 were highly expressed in tumor samples." (PMID 38610001, 2024). "We then demonstrated that TWIST1 was required for tumor proliferation in MET altered NSCLC both in vitro and in vivo." (PMID 38485737, 2024). "A strong positive correlation was detected between the expression of INHBA and EMT transcription factors SNAI1 (Rho = 0.62), SNAI2 (Rho = 0.82), and TWIST1 (Rho = 0.69) in the primary tumor." (PMID 38329386, 2024). "Together, these findings suggest a sequential transcriptional activation mechanism for OPN expression, driven directly by Twist1 and indirectly by Twist1-downstream SATB1 in tumor ECs." (PMID 38416830, 2024). "Previous studies have found that the TWIST1 transcription factor can promote tumor metastasis and induce EMT." (PMID 39593172, 2024). "Consistent with the CNV results, the expression of tumor-associated genes, including KIR3DL2, TOX, TWIST1, and GTSF1, upregulated along the CD4+ T-cell trajectory." (PMID 39963655, 2024). "To gain molecular insights into the regulation of Mφ immunosuppression by endothelial Twist1, we determined transcriptome changes in tumor ECs treated with CRISPR/sgRNA targeting Twist1." (PMID 38416830, 2024). "This decision was guided by the fact that the analysis of human expression data provided more comprehensive evidence for the upregulation of Snai1 in the tumor endothelium than for Slug and Twist1." (PMID 39095583, 2024). "We next examined the effects of EC-specific knockout of Twist1 on tumor growth and animal survival in syngeneic mouse GL261 and genetically engineered RCAS models." (PMID 38416830, 2024). "In contrast to Twist1 OE, OE of Snai1 in the tumor cells increased the relative and absolute volume of CD31+ PVs in the VTSs." (PMID 38678014, 2024). "We report the identification of a distinct mesenchymal-like population of tumor ECs that form an immunosuppressive vascular niche for Mφ polarization through a Twist1/AT-rich sequence binding protein 1 (SATB1)/osteopontin (OPN)–dependent mechanism." (PMID 38416830, 2024). "In sum, our work suggests a multidimensional mechanism controlling tumor immunity through spatial interaction between tumor ECs and Mφs, in which a Twist1/SATB1/OPN axis serves as a regulatory node for tumor immunosuppression." (PMID 38416830, 2024). "Previous studies have suggested the potential involvement of Sox6 in the EMT of numerous tumor cells, engaging various downstream pathways/factors, including Twist1, the Akt pathway, and the Wnt/β-catenin pathway." (PMID 38294713, 2024). "Increased levels of transcription factors like Snail, Twist1 and Zeb1 enhances the sensitivity of tumor cells to ferroptosis." (PMID 38469234, 2024). "Genetic or pharmacological ablation of Twist1 reverses tumor immune suppression and circumvents tumor resistance to CAR T cell immunotherapy." (PMID 38416830, 2024). "Here, our study identifies a mesenchymal-like subpopulation of ECs as a major source of tumor immunosuppression, interacting with tumor Mφs to drive immunosuppressive phenotypes via Twist1/SATB1-dependent expression and secretion of OPN." (PMID 38416830, 2024).
tumor (continued). "Together, these results identify a mesenchymal-like subpopulation of tumor ECs with up-regulated Twist1 expression, which potentially drives immunosuppressive Mφ polarization." (PMID 38416830, 2024). "The EMT transcription factor (EMT-TF), TWIST1, is overexpressed in approximately 40% of NSCLC and is associated with a more aggressive tumor phenotype, increased risk of metastasis, and worsened patient prognosis." (PMID 38485737, 2024). "The molecular mechanism underlying OPN overexpression in cancer remains largely unclear, and our study uncovers a sequential Twist1/SATB1 transcriptional activation mechanism that leads to OPN expression in tumor ECs." (PMID 38416830, 2024). "Our present work reveals a mechanism that acts as an upstream determinant of functional Mφ regulation in the tumor microenvironment, namely, Twist1 in a vascular niche, serving as an alternative intervention target." (PMID 38416830, 2024). "TWIST1 is a basic helix-loop-helix (bHLH) transcription factor that promotes tumor metastasis by initiating EMT and degrading ECT." (PMID 37916166, 2023). "The TWIST1/2 signaling pathway promotes tumor invasion and metastasis by regulating the transformation of tumor epithelial mesenchymal." (PMID 36979146, 2023). "It was found that the expression of TWIST1 mRNA was significantly increased in PANC tissues compared with non-tumor tissues (P < 0.01)." (PMID 37403096, 2023). "We also show that the functional shift is TWIST1-dependent and is consistent with mesenchymal-to-epithelial transition, which is key to establishment of secondary tumor growth." (PMID 36674745, 2023). "While TWIST1 appears to have a clear tumor promoting role in AML cells, its expression in the bone marrow microenvironment seems to have a more tumor inhibiting impact on AML cells." (PMID 37600794, 2023). "USP29 directly binds, deubiquitinates, and stabilizes TWIST1, which in turn promotes TWIST1‐driven tumor progression in TNBC." (PMID 36782089, 2023). "Under hypoxia, Twist1 expression in tumor cells is directly induced by hypoxia-inducible factor (HIF)-1α and -2α." (PMID 37208442, 2023). "FBXO3 functions as a USP4 binding partner to protect USP4 from degradation, which in turn leads to stabilization of Twist1, thereby promoting cell migration and tumor metastasis." (PMID 38134227, 2023). "TWIST1 is a basic helix-loop-helix (bHLH) transcription factor and plays essential and pivotal roles in both embryonic development and tumor initiation." (PMID 37748319, 2023). "Hypoxic conditions as a result of rapid tumor growth and insufficient vasculature can also lead to TWIST1 expression via HIF-1α." (PMID 38139368, 2023). "Twist1 is a basic helix–loop–helix (bHLH) transcription factor significantly contributing to tumor metastasis, tumor initiation, and primary tumor growth." (PMID 36672299, 2023). "Mesenchymal-like OVCAR8 cells displaying resistance to cisplatin were resensitized via the inhibition of TWIST1, leading to reduced Akt activation under cell culture conditions and reduced tumor growth in vivo." (PMID 37568736, 2023). "In this study, we found that several CAF-related markers, including PDGFR-β, α-SMA, FAP-α, S100A4/FSP1, collagen type I, and Twist1, were expressed at high levels in stromal CAFs in the proximity of tumor areas in BMs." (PMID 36860926, 2023). "Among all these genes, TWIST1 is a vital transcription factor mediating the progression of epithelial-mesenchymal transition and tumor metastasis." (PMID 38273850, 2023). "Higher expression of Twist1 was strongly related to larger tumor size (p = 0.002) and poorer degree of differentiation (p = 0.034)." (PMID 37277751, 2023). "TWIST1 activity is closely associated with EMT, correlating with tumor growth, metastasis and drug resistance, thereby diminishing the survival of cancer patients." (PMID 37696879, 2023).
tumor (continued). "KLF4, as an antiproliferative factor in differentiated epithelium, knockdown significantly reduces TWIST1-induced metastatic activity in vitro and in vivo and decreases tumor initiation capacity." (PMID 37598158, 2023). "Together, our results uncover a novel cell cycle independent function of CDK1 to promote tumor progression through stabilizing TWIST1 in TNBC." (PMID 36782089, 2023). "A study on EMT in malignant melanoma reported that SNAI2 and ZEB2 transcription factors are expressed in normal melanocytes and behave as tumour-suppressor proteins, whereas TWIST1 and ZEB1 favour neoplastic transformation in melanocytes." (PMID 36766756, 2023). "The prominent role of Twist1 in tumor progression is to induce EMT and extracellular matrix degradation." (PMID 37208442, 2023). "Together, these results uncover a previously unrecognized function of USP29 in tumor progression of TNBC through stabilizing TWIST1." (PMID 36782089, 2023). "Gene annotation and pathway analysis on the unique identified H3K4me3 peaks from KO tumours corroborated these findings by showing enrichment of Twist1, Twist2 and extracellular matrix organization." (PMID 36933062, 2023). "TWIST1 also facilitates tumor invasion and metastasis by promoting EMT, formation of invadopodia, intravascular migration, extravasation, and vasculogenic mimicry (VM)." (PMID 36674745, 2023). "In glucose metabolism, Twist1 mainly participates in Warburg effect, a phenomenon that tumor tissues metabolize approximately tenfold more glucose into lactate than normal tissues under the aerobic conditions, thus promoting tumor metastasis and progression." (PMID 37784111, 2023). "Given that the JICD1 transcriptional complex regulates cell migration and invasion via TWIST1, we investigated the functional consequences of JICD1/SMAD3-TWIST1-mediated cell migration on tumor aggressiveness in vivo." (PMID 38092725, 2023). "CDK1‐mediated phosphorylation is essential to activate USP29 toward TWIST1 and promote tumor progression in TWIST1 dependent manner." (PMID 36782089, 2023). "In support of this, SRC activation was strongly correlated with the PC1 and EMT signatures and the EMT genes (e.g. ZEB2, TWIST1) that are known to promote migration, invasion and metastasis and to induce tumor cells to acquire stem cell characteristics." (PMID 35272617, 2022). "Twist1 phosphorylation increases tumor cell motility in squamous cell carcinoma of the head and neck." (PMID 35781329, 2022). "The occurrence of EMT in tumor cells and the stimulation of tumor metastasis are promoted by TWIST1." (PMID 35052775, 2022). "TWIST1 can promote tumor cell invasion and metastasis, and act as a vital regulator in the EMT process." (PMID 35517426, 2022). "HIF1α was identified as a transcription factor of numerous genes related to the EMT, stem-like properties and metastasis of tumor cells, including Twist1, ZEB1 and ZEB223,24,43." (PMID 35941273, 2022). "An increase in angiogenesis related to tumor progression is also promoted by TWIST1, which acts by increasing the production of vascular endothelial growth factors." (PMID 35052775, 2022). "Using an in vivo model for transcriptomic analyses, we then unveiled the impact of CRISPR/Cas9-mediated TWIST1 silencing on NB tumor growth, metastatic colonization, and the reorganization of the tumor microenvironment (TME)." (PMID 35022561, 2022). "For example, EMT transcriptional factors, including Snail, Zeb1, and Twist1, can attract cancer-related immune cells and shape tumor microenvironment into a protumor subtype." (PMID 35990996, 2022). "The reported cadherin switch, and expression of EMT-associated transcription factors TWIST-1, ZEB-1, and HIF-1α were highly indicative for EMT events in the tumor, possibly explaining the metastatic behavior." (PMID 35215208, 2022). "It has been shown that TWIST1 plays a role either in the EMT-induced CSC phenotype or tumor stemness-induced EMT." (PMID 36553636, 2022).
tumor (continued). "TWIST1 enhances the ability of primary tumor cells to undergo EMT and thus promotes invasive and metastatic cancer phenotypes." (PMID 36127329, 2022). "As a master regulator of morphogenesis and a TGF- cooperation factor, Twist1 plays a crucial role in tumor metastasis." (PMID 36471885, 2022). "While the roles of Twist1 in cancer cells are well studied, little is known about the involvement of Twist1 in tumor stroma cells." (PMID 35331296, 2022). "Correlation test results of coexpression of HOXA9 and tumor-related transcription factors showed that HOXA9 was copositively correlated with Twist1." (PMID 35783150, 2022). "Secondly, suppression of TWIST1 by CRISPR/Cas9 results in a reduction of tumor growth and metastasis colonization in immunocompromised mice." (PMID 35022561, 2022). "Our data from ChIP experiments suggest that FoxO1 inhibited the invasion and metastasis of tumor cells by transcriptionally regulating the Twist1 promoter." (PMID 33772986, 2022). "In this study, we initially revealed the correlation between the expression of TWIST1/2 and NB clinical prognostic factors in silico on primary NB gene expression datasets and in tumor tissue microarrays." (PMID 35022561, 2022). "GATA3 and TWIST1 are involved in the E-cadherin expression, which determines how potent the tumor cell migration is." (PMID 35408897, 2022). "To examine the correlation between TWIST1 and UCA1, the lncRNA that had been expressed in all three cell lines, we performed real-time PCR for UCA1 in twenty tumor and tumor-adjacent normal tissue samples with confirmed overexpression of TWIST1 (logFC > 2)." (PMID 35949302, 2022). "Our data showed a higher expression of both SNAI1 and TWIST1 in EC-adjacent tissues than in the matched tumor samples." (PMID 36140779, 2022). "In EC, the expression of cancer-promoting genes, MYC, NR5A2, SNAI1, and TWIST1, was found to be significantly higher in tumor-adjacent tissues than in the matched tumors." (PMID 36140779, 2022). "For example, TWIST1 plays an important role in the vascular invasion and lung metastasis of tumor cells." (PMID 35052775, 2022). "This is consistent with previous studies linking ZEB1, SNAI1 and TWIST1 with a mesenchymal phenotype of tumor cells in CRC." (PMID 35565409, 2022). "Both grade I and II showed several hotspots with high expression (3+) (IRS = 12) of TWIST1, while substantial area of tumor tissue showed low (1+) TWIST1 nuclear expression." (PMID 35163107, 2022). "A large number of studies have found that EMT plays a key role in tumor invasion and metastasis, and TWIST1 has been identified as an important regulating factor in the EMT process." (PMID 35052775, 2022). "The marked connection observed between the TWIST1-tumor-stroma signature and the stromal DE genes by STRING analysis further support their role in mediating the NB-associated alterations in the tumor stroma." (PMID 35022561, 2022). "Studies have reported that Twist1 is a transcription factor that plays a role in cell development, tumor metastasis, and epithelial-mesenchymal transition in vertebrates." (PMID 36254231, 2022). "A second possibility derives from the observation that AMPK has been shown to induce EMT in tumor cells by increasing the expression of the EMT master TF Twist1." (PMID 35326492, 2022). "First, our outcomes exhibited that the TWIST1 and FBXO45 expression levels were negatively associated in TNBC tumour tissues, and FBXO45 regulated TWIST1 expression in TNBC cells." (PMID 35802537, 2022). "The presence of TWIST1 expression in CRC was reported mainly in cancer cells with a mesenchymal phenotype located in the tumor stroma." (PMID 35565409, 2022).